SIRT3 (sirtuin 3)
Diseases named in the same sentence as SIRT3 in open-access papers (continued):
Sharing a sentence is not in itself a finding about the gene and the disease.
Sepsis (continued). "It has been reported that SIRT6 and SIRT3 work closely with SIRT1 in the sepsis adaptation stage to jointly regulate energy shifts, promote mitochondrial-nuclear exchange, and accelerate the development of immunosuppression." (PMID 30533222, 2018). "Decreased SIRT1/SIRT3 protein levels correlate with increased glycolysis and its adverse effect on cardiac dysfunction during early sepsis." (PMID 30216989, 2018). "Since the therapeutic effect of SIRT3 in sepsis is unrelated to inflammation, its activation can alleviate sepsis at any stage." (PMID 30533222, 2018). "The involvement of autophagy in the effect of SIRT3 on sepsis-induced kidney injury was further examined using the autophagy inhibitor 3-methyladenine (3-MA)." (PMID 30487750, 2018). "The role of SIRT3 in sepsis-induced AKI was investigated further by overexpressing SIRT3 in mice subjected to CLP or sham surgery." (PMID 30487750, 2018). "We demonstrated sustained increase in SIRT1 and SIRT3 protein levels during the hypo-inflammatory phase of sepsis in which fatty acid oxidation replaces glycolysis as the predominant fuel source." (PMID 30216989, 2018). "This suggests that SIRT3 support of fatty acid oxidation during sepsis tolerance is cardio protective." (PMID 30216989, 2018). "Inhibiting glycolysis by 2-deoxyglucose, a hexokinase-2 inhibitor, prevents cardiac dysfunction and glycolysis along with increased SIRT1/SIRT3 levels during early sepsis." (PMID 30216989, 2018). "The blockage of autophagy induction largely abolished the protective effect of SIRT3 in sepsis-induced AKI." (PMID 30487750, 2018). "The overexpression of SIRT3 promoted autophagy concomitant with p-AMPK, upregulation of p-mTOR downregulation and confirmed the involvement of AMPK/mTOR-related autophagy, in the protective effect of SIRT3 against sepsis-induced AKI." (PMID 30487750, 2018). "We provided evidence of a critical role for PKCα in mediating the phosphorylation of T. gondii GRA8 that facilitates interactions between GRA8 and ATP5A1 or SIRT3, thereby contributing to metabolic resuscitation against sepsis and cancer." (PMID 29869623, 2018). "The results indicated that CypD played the important role in cognitive dysfunction induced by sepsis, and SIRT3 overexpression attenuated cognitive impairment in sepsis mice." (PMID 28236057, 2017). "In conclusion, CypD deacetylation and SIRT3 overexpression in hippocampus attenuated learning and memory dysfunction induced by sepsis." (PMID 28236057, 2017). "This study suggested that the activation of SIRT3 alleviated learning and memory dysfunction induced by sepsis." (PMID 28236057, 2017). "Taken together, these results confirm that SIRT3 protects against sepsis-induced AKI via the ROS/caspase pathway." (PMID 27620507, 2016). "Using loss- and gain- of function approaches and endotoxin (LPS)-induced septic model, we have investigated the fundamental role of Sirt3 in the regulation of endothelial/pericyte interactions, vascular integrity and permeability during sepsis." (PMID 26868537, 2016). "In the present study, the role of SIRT3 in mitochondrial damage associated with AKI was examined using a caecal ligation and puncture (CLP) model of sepsis-induced AKI in a SIRT3 knockout mouse model." (PMID 27620507, 2016). "Our data demonstrated that Sirt3 was necessary for the pericyte function and vascular permeability in sepsis." (PMID 26868537, 2016). "Our study demonstrates the importance of SIRT3 in preserving vascular integrity by targeting pericytes in the setting of LPS-induced sepsis." (PMID 26868537, 2016). "In sepsis, LPS suppresses Sirt3 expression, which disrupts angiopoietins/Tie-2 and HIF-2α/Notch3 signaling pathways; thus leading to a reduction of pericyte/capillary coverage, subsequently promoting vascular leakage, inflammation and end-organ dysfunction." (PMID 26868537, 2016).
Sepsis (continued). "Here, we showed that SIRT3 protects against sepsis-induced kidney alterations by attenuating inflammatory responses, modulating tubular cell apoptosis, and decreasing ROS-related mitochondrial damage." (PMID 27620507, 2016). "Moreover, SIRT3 holds promise as a marker for diagnosing and prognosticating sepsis, given its ability to predict mortality in septic patients." (PMID 38690282, 2024). "Recognizing the pivotal role of glycolytic metabolism in sepsis-induced organ injury, the therapeutic administration of 2-deoxy-D-glucose (2-DG) to inhibit glycolysis has been shown to upregulate SIRT3 and p-AMPK expression, thereby significantly ameliorating sepsis-induced renal injury." (PMID 39712019, 2024). "Further, we found that Plantainoside D (PD), an effective component of Plantago asiatica L could improve sepsis ALI by regulating Sirt3/NLRP3 pathway related proteins." (PMID 37494665, 2023). "However, it remains elusive if NAD+ repletion prevents SIRT3 inhibition in alleviating organ dysfunction during sepsis." (PMID 38057866, 2023). "Sirt3 KO or silence significantly aggravated sepsis induced ALI and MLE-12 cell injury." (PMID 37494665, 2023). "High level of SIRT3 protects against sepsis-induced AKI by modulating AMPK/mTOR-mediated autophagy." (PMID 37215112, 2023). "Upregulation of SIRT3 has been reported to protect against sepsis-induced AKI." (PMID 37215112, 2023). "Since NAD+ is an important antioxidant mechanism by directly balancing the redox status and/or indirectly promoting SIRT1/3-mediated antioxidant defences, decreased NAD+ may promote mitochondrial dysfunction and organ injury in sepsis through SIRT3 inhibition." (PMID 38057866, 2023). "Sirt3 contains the switches that control mitochondrial energy metabolism, it may be a potential strategy for future sepsis treatments that target mitochondria." (PMID 35729330, 2022). "In our research, Sirt3 showed good clinical significance in sepsis." (PMID 35729330, 2022). "The clinical significance of Sirt3 in sepsis was confirmed by our study." (PMID 35729330, 2022). "Additionally, Sirt3 can predict mortality of sepsis (AUC = 0.746, 95% CI 0.571–0.921, P = 0.022), patients with serum Sirt3 < 10.07 pg/ml have a lower 28-day survival (log-rank P = 0.008)." (PMID 35729330, 2022). "The ROC curves of Sirt3 for the diagnosis of sepsis and septic shock were also displayed." (PMID 35729330, 2022). "SIRT3 primarily localizes in mitochondria, protects mitochondrial function, and upregulates autophagy; therefore, we suspected that melatonin-mediated SIRT3 activation in response to sepsis might involve mitochondrial protection and autophagy promotion." (PMID 33790896, 2021). "Many literatures have reported the role of SIRT3 on autophagy activation in non-sepsis models." (PMID 33790896, 2021). "We confirmed this mechanistic effect in a CLP-induced sepsis model of intestinal SIRT3 conditional-knockout mice, and found that melatonin preserved mitochondrial function and induced autophagy of small-intestine epithelial cells; these effects were dependent on SIRT3 activation." (PMID 33790896, 2021). "To date, the role of SIRT3 activation on autophagy in sepsis is rarely reported." (PMID 33790896, 2021). "In the present study, SIRT3 knockout (KO) mice were used to construct a sepsis model." (PMID 34249270, 2021). "Third, the SIRT3 conditional knockout was induced in the intestine, which includes the small and large intestines; thus, we cannot eliminate the possibility that melatonin-rich colon also affects sepsis-induced bowel injury prognosis." (PMID 33790896, 2021). "The nuclear SIRT1 and mitochondrial SIRT3 regulate mitochondrial biogenesis during sepsis." (PMID 35052507, 2021). "This study has shown, to the best of our knowledge, for the first time that melatonin alleviates sepsis-induced small-intestine injury, at least partially, by upregulating SIRT3-mediated oxidative-stress inhibition, mitochondrial-function protection, and autophagy induction." (PMID 33790896, 2021).
Sepsis (continued). "We also confirmed this mechanism in a sepsis model developed using SIRT3 conditional-knockout mice." (PMID 33790896, 2021). "Based on our results, drugs targeting the SirT3-AMPK-mitochondrial biogenesis axis may benefit patients suffering from sepsis-related myocardial injury." (PMID 32721927, 2020). "We have previously shown that single deficiency in either SIRT3 or SIRT5 had no impact on host defenses in a large panel of preclinical models of sepsis." (PMID 31632409, 2019). "SIRT3/5−/− mice should be tested in other preclinical models of sepsis." (PMID 31632409, 2019). "In addition, nuclear SIRT1 can guide RELB to differentially induce SIRT3 expression, and it also can increase mitochondrial biogenesis, which alters bioenergetics during sepsis adaptation." (PMID 30533222, 2018). "SIRT3 appears to be a potential target for sepsis because of its mitochondrial protective effects." (PMID 30533222, 2018). "We studied the role of SIRT3 during the late/hypo-inflammatory phase of sepsis." (PMID 30216989, 2018). "The mechanism underlying the protective effect of SIRT3 through modulation of autophagy was further investigated by assessing the levels of the autophagy regulators AMPK and mTOR in kidney tissues exposed to sepsis-induced AKI." (PMID 30487750, 2018). "In this article, we investigated the role of autophagy, mediated by a mammalian target of rapamycin (mTOR) and AMP-activated protein kinase (AMPK), in the protective effect of SIRT3, against sepsis-induced AKI, in a mouse model of cecal ligation and puncture (CLP)." (PMID 30487750, 2018). "We therefore proposed that SIRT3 may be potential therapeutic target for preventing sepsis-induced microvascular permeability and end-organ failure." (PMID 26868537, 2016). "Interestingly, the relationship between the functions of nuclear SIRT1 and mitochondrial SIRT3 is coordinated during the hypoinflammatory phase of sepsis in THP1 human promonocytes." (PMID 28003866, 2016). "Here, we used a murine caecal ligation and puncture (CLP) model of sepsis-induced AKI to study the role of sirtuin 3 (SIRT3), a NAD+ dependent deacetylase critical for the maintenance of mitochondrial viability, in AKI-related renal tubular cell damage and explored the underlying mechanisms." (PMID 27620507, 2016). "Based on the importance of the SIRT1/3 axis in the pathogenesis of severe shock, we hypothesized that SIRT3 may play a role in sepsis." (PMID 28003866, 2016). "By tailoring interventions to specific molecular nodes—whether enhancing PINK1-Parkin flux in fibrosis, restoring SIRT3 activity in sepsis, or targeting FUNDC1 in hypoxia—researchers are pioneering strategies to break the cycle of mitochondrial dysfunction and inflammation." (PMID 41026942, 2025). "SIRT1 reduces the expression of inflammatory cytokines by directly deacetylating the NF-κB inhibitory subunit, while SIRT3 mainly alleviates oxidative stress-induced damage by maintaining mitochondrial function and enhancing the activity of antioxidative enzymes, improving sepsis-induced MODS." (PMID 38690282, 2024). "In conclusion, Sirt3 may be the important molecular targets for sepsis ALI." (PMID 37494665, 2023). "However, Sirt3 has been rarely studied in patients with sepsis." (PMID 35729330, 2022). "The purpose of this study is to determine whether the levels of serum Sirt3 correlate with disease severity and perfusion indicators in septic patients, as well as to assess the clinical value of Sirt3 as a potential novel marker for sepsis diagnosis and mortality prediction." (PMID 35729330, 2022). "Therefore, the present study is aimed at investigating whether Sirt3 alleviates sepsis-induced inflammation by maintaining lung microvascular endothelial barrier integrity via the interaction of β-catenin and VE-cadherin." (PMID 34630854, 2021).
Sepsis (continued). "In addition, in an AKI model induced by sepsis, researchers also observed that Sirt3 plays a protective role against mitochondrial damage in the kidney by attenuating ROS production, inhibiting the NRLP3 inflammasome, attenuating oxidative stress and down‐regulating pro‐inflammatory cytokines." (PMID 32281286, 2020). "Moreover, SIRT3 knock out mice show increased acute kidney injury during sepsis." (PMID 30216989, 2018). "Imbalanced mitochondrial dynamics stimulate pro-inflammatory polarization of alveolar macrophages in sepsis-induced ALI, while the deacetylation of optic atrophy protein 1 (OPA1) facilitated by SIRT3 enhances MD equilibrium, thus alleviating lung injury." (PMID 40867920, 2025). "In alveolar macrophages of sepsis-induced ALI, there was a noted decrease in SIRT3 protein expression alongside an increase in OPA1 acetylation." (PMID 40867920, 2025). "The lactate/SIRT3/AMPK pathway, by inhibiting aerobic glycolysis, alleviates sepsis-induced kidney injury, indicating a potential reclassification of lactate from a “metabolic waste” to a therapeutic target for organ damage in sepsis." (PMID 39712019, 2024). "Proteomics, immunoprecipitation, molecular docking techniques, and Sirt3 knockout (KO) mice and silence MLE-12 cells were used to search for biomarker and treatment measures for sepsis ALI." (PMID 37494665, 2023). "Our previous study found that sepsis disrupted ATP synthase by calpain-mediated cleavage of its subunit ATP5A1, an event facilitated by impaired SIRT3 activity due to NAD+ depletion." (PMID 38057866, 2023). "Our research showed a strong correlation between Sirt3 and SOFA, which is consistent with the results of most basic experiments on sepsis-induced MODS." (PMID 35729330, 2022). "SIRT3 overexpression has been shown to be protective in sepsis and cisplatin induced AKI and SIRT3 knockout resulted in worse injury in sepsis induced AKI." (PMID 34501442, 2021). "In the sepsis model, depletion of SIRT3 also induces excessive acetylation of enzymes in the TCA cycle and production of lactate and NADH, which accordingly deteriorate sepsis-induced cardiac dysfunction." (PMID 34957264, 2021). "Our study reveals that melatonin alleviates sepsis-induced small-intestine injury by upregulating SIRT1 and SIRT3." (PMID 33790896, 2021). "In sepsis-induced AKI models, SIRT3 can protect against mitochondrial damage in the kidney by reducing oxidative stress and inflammatory cytokines." (PMID 34220520, 2021). "The sepsis-induced AKI model was constructed in the wild-type and SIRT3 knockout (KO) mice, and the levels of serum creatinine (Scr) and plasma kidney injury molecule 1 (pKIM-1) in mice were detected by ELISA." (PMID 34249270, 2021). "Overexpression of SirT3 increases AMPK activity and improves mitochondrial biogenesis, which sustains mitochondrial function and reduces sepsis-related cardiomyocyte injury." (PMID 32721927, 2020). "In a sepsis AKI model, SIRT3 was shown to have a protective effect on renal mitochondrial injury by reducing the production of ROS, and decreasing the release of IL-1β and IL-18." (PMID 32175320, 2020). "We studied the effects of SirT3, AMPK, and mitochondrial biogenesis on sepsis-induced myocardial injury." (PMID 32721927, 2020). "In the present study, we found that SirT3 downregulation and AMPK inactivation are the primary subcellular events in the progression of sepsis-induced myocardial damage." (PMID 32721927, 2020). "SIRT3 overexpression promoted autophagy, upregulated p-AMPK and downregulated p-mTOR in CLP mice, attenuating sepsis-induced AKI, tubular cell apoptosis, and inflammatory cytokine accumulation in the kidneys." (PMID 30487750, 2018). "In this study, we further examined the role of SIRT3 in the mitochondrial damage associated with AKI in a cecal ligation and puncture (CLP) model of sepsis-induced AKI, in SIRT3 knockout mice." (PMID 30487750, 2018).
Sepsis (continued). "We discovered that in cell and lean mouse models of sepsis that nuclear SIRT-1 couples with nuclear NFκB p65/ RelB, nuclear SIRT-6 and mitochondrial SIRT-3 as homeostasis checkpoints during acute sepsis-inflammation." (PMID 27500833, 2016). "SIRT3 further enhances the efficiency of the oxidative phosphorylation chain by deacetylating the pivotal enzyme SDHA, mitigating electron leak and consequently reducing the generation of ROS during sepsis and ischemia-reperfusion." (PMID 38690282, 2024). "In conclusion, Sirt3 is an important regulatory factor involved in acute lung injury in sepsis, we found that PD can significantly improve sepsis ALI, and its mechanism is related to the regulation of Sirt3/NLRP3 signal pathway, and the deeper mechanism needs to be further studied." (PMID 37494665, 2023). "When sepsis‐induced AKI occurs, the expression of Sirt3 is reduced, resulting in a decrease in the deacetylation level of YME1L1 and a decrease in the expression of L‐OPA, which in turn reduces mitochondrial fusion and increases fission, ultimately leading to mitochondrial dysfunction and apoptosis." (PMID 36433732, 2023). "The present study aims to further study the regulation mechanism of SIRT3 on the mitochondrial function and apoptosis of kidney tubular epithelial cells (KTEC) in septic mice and to provide a new therapeutic target for AKI induced by sepsis." (PMID 34249270, 2021). "In a sepsis model of cecal ligation and puncture, nicotinamide adenine dinucleotide NAD-dependent protein deacetylase SIRT3, a member of the mammalian sirtuin family of proteins, provided protection from sepsis-induced AKI through AMPK/mTOR-regulated autophagy." (PMID 31936109, 2020). "Finally, SIRT3−/− and SIRT5−/− mice behaved like wild-type mice in models of sepsis requiring neutrophils to fight the infectious agents." (PMID 31632409, 2019). "Unlike SIRT1 and SIRT2, SIRT3 activation and overexpression show several positive effects in sepsis treatment." (PMID 30533222, 2018). "Given the role of the NLRP3 inflammasome in sepsis-induced AKI, we investigated whether SIRT3 knockout had an effect on AKI-related inflammatory responses by assessing NLRP3 levels and function in response to CLP." (PMID 27620507, 2016). "The findings reveal that melatonin leverages a SIRT3-dependent pathway to enact deacetylation of SOD2, thereby safeguarding mitochondrial quality control in pulmonary epithelial cells, ultimately mitigating the sepsis-induced damages, inflammation, oxidative stress, and cell apoptosis." (PMID 38690282, 2024). "Additionally, SIRT3−/− mice were not particularly susceptible to cecal ligation and puncture (CLP), a stringent model of sepsis." (PMID 31632409, 2019). "In addition, the benefit effect of melatonin on SIRT3 activation was considerably blocked by MT1/MT2-nonselective antagonist luzindole but was not blocked by MT2-selective antagonist 4P-PDOT in small intestine 8 h following sepsis." (PMID 33790896, 2021). "The correlation between serum Sirt3 and PCT was examined in the groups with sepsis (Pearson: r2 = − 0.409, P = 0.015), but not in the groups with septic shock (r2 = 0.046, P = 0.866)." (PMID 35729330, 2022). "SIRT3 mRNA expression evolved differently with an increasing effect of dietary EPA (+61 and +51% for the Sham and Sept subgroups, p < 0.05) and no significant influence of sepsis." (PMID 31534623, 2019).